MIR132 (microRNA 132)
Synonyms: hsa-mir-132; MIRN132; miRNA132; mir-132
Gene: MicroRNA gene on chromosome 17 (2,049,908 to 2,050,008, reverse strand). Ensembl gene ENSG00000267200.
Gene Ontology:
Biological process: miRNA-mediated post-transcriptional gene silencing
Cellular component: RISC complex
Homologues: Orthologues: dog MIR132 (99% identical), pig MIR132 (99% identical), rat Mir132 (98% identical), tropical clawed frog xtr-mir-132 (67% identical), guinea pig MIR132 (64% identical), mouse Mir132 (64% identical), zebrafish dre-mir-132-2 (63% identical), zebrafish dre-mir-132-1 (62% identical). Paralogues in human: MIR212 (53% identical).
Diseases named in the same sentence as MIR132 in open-access papers:
MIR132 is named in the same sentence as 7 diseases in open-access papers, as found by Europe PMC text mining. Sharing a sentence is not in itself a finding about the gene and the disease. The quoted sentences say what the papers report.
cognitive decline (1 paper, 2018). "Together with this core variable set, either MIR132, beta-amyloid, TAR DNA binding protein 43 (TDP-43), IGFBP5, or histone coacetylation modules could explain the mediation of AD-PRS to cognitive decline." (PMID 30349450, 2018).
neurologic disorder (1 paper, 2020). "Finally, Pafah1b1 (targeted by Mir132), has been associated with the abnormal migration of cortical neurons and with neurologic disorder in mice and humans." (PMID 32093602, 2020).
MIR132 also shares sentences with these, for which no sentence is quoted: Cognitive impairment (1 paper); epilepsy (1); Stroke (1); tumor (1); Zinc deficiency (1).